MTOR (mechanistic target of rapamycin kinase)
Diseases named in the same sentence as MTOR in open-access papers (continued):
Sharing a sentence is not in itself a finding about the gene and the disease.
breast cancer (continued). "Our data predict that both autophagy and mTOR inhibition may be useful therapeutic approaches for breast cancer." (PMID 23818925, 2013). "It has been recently shown that treatment of breast cancer cells with MEK or mTOR inhibitors and either Doxorubicin or Tamoxifen results in a synergistic response that highlights the advantages of combining classical chemotherapy with targeted adjuvant treatments." (PMID 23341997, 2013). "However, constitutively active mTOR has been found to fully ablate the beneficial effects of CR on mammary tumor growth." (PMID 23986086, 2013). "Nevertheless, outside patients with renal cell carcinoma, refractory mantle cell lymphoma and ER-positive/HER2-negative breast cancer when combined with hormone therapy, the antitumour activity of the first generation of mTOR inhibitors (rapalogs) has fallen short of expectations." (PMID 24237791, 2013). "We observed a difference in the ATP levels between STK11−/−/NIC mammary tumors and WT mammary tissue, reflective of the loss of LKB1 expression and therefore regulation of AMPK activity, leading to hyperactivation of mTOR through both mTORC1 and mTORC2 pathways." (PMID 23451056, 2013). "Another pathway of considerable active interest in breast cancer is the PI3K/mTOR pathway." (PMID 23662165, 2013). "In addition, arachidonic acid (20:4n-6) activates amino acid-independent mTOR signalling in breast cancer cells, inducing proliferation and angiogenesis; however, ceramide induces autophagy by inhibiting mTOR signalling in several cell types." (PMID 24135873, 2013). "Girdin may regulate the biological behavior of breast cancer via the PI3K/Akt/mTOR pathway, and thus, serve as a potential new target for breast cancer treatment." (PMID 23760650, 2013). "In addition, mTOR inhibitors also show greatly anti-tumor effects for advanced breast cancer, mantle cell lymphoma (MCL) and pancreatic neuroendocrine tumors." (PMID 23785409, 2013). "Given the ability of SFN to induce autophagy in breast cancer cell lines, we hypothesized that it can negatively influence activity of mTOR." (PMID 23389114, 2013). "IIi was also found to inhibit mTOR activity and induce autophagy in breast cancer cells." (PMID 23761818, 2013). "This study evaluates the clinical value of mTOR effectors in breast cancer." (PMID 24131622, 2013). "Recently, Hursting and Colleagues reported that treatment with the mTOR inhibitor everolimus abolishes the tumorigenic effects associated with obesity, improves calorie restriction-mediated anticancer activity, and blocks mammary tumor development and mTOR activation." (PMID 24069582, 2013). "As reviewed below, progression on lapatinib is often associated with heightened mTOR or MEK signaling; thus, coinhibition of PI3K/mTOR and MEK is a plausible strategy for treating lapatinib-naïve or lapatinib-refractory HER2-positive breast cancer." (PMID 23227361, 2012). "Collectively these data indicate that activation of AKT/mTOR pathway is involved in BRCA1-deficiency mediated tumorigenesis and that the inhibition of AKT/mTOR pathway can be used as a target for treatment of BRCA1-deficient breast cancers." (PMID 26097796, 2012). "In addition, we show for the first time that SESN2 blocks IR-induced Akt-mTOR signalling and acts as a radiation sensitizer in breast cancer cells." (PMID 22363791, 2012). "In xenografts derived from the breast cancer cell line MCF7 and the pancreatic carcinoid cell line BON, both harboring an activating PIK3CA mutation, treatment with the allosteric mTOR inhibitor Rapamycin (Sirolimus) was associated with a significant decrease in tumor volume." (PMID 22970424, 2012). "We next examined the effect of honokiol on mTOR activity in breast cancer cells." (PMID 22353783, 2012). "As the mTOR pathway is frequently active in HER2 overexpressing breast cancers and regulates c-Myc activity, our results imply that the corresponding tumor cells might frequently express constitutive Bim." (PMID 21899728, 2011).
breast cancer (continued). "mTOR activation occurs frequently in breast cancer and results in a poorer prognosis." (PMID 22203527, 2011). "Previous studies demonstrated Akt could regulate the activation of GSK-3β, p70S6K1 and mTOR, and all of them were able to activate Rac1, suggesting that hypoxia stimulates Rac1 activation in breast cancer cells by activating PI3K/Akt signaling." (PMID 21980400, 2011). "The authors conclude that a combination therapy with mTOR inhibitors and cisplatin could be a useful therapeutic strategy for the treatment of basal-like breast cancers." (PMID 21804822, 2011). "Furthermore, rapamycin lowered the IC50s for doxorubicin, etoposide and 4HT in the cells which expressed ΔAkt-1(CA), demonstrating a potential improved method for treating certain breast cancers which have deregulated PI3K/PTEN/Akt/mTOR signaling." (PMID 21730367, 2011). "Based on these data, we hypothesise a signalling pathway depicting cross-talk between survival and death signalling pathways in α-TEA alone and α-TEA+MEK or mTOR inhibitor-induced apoptosis in human breast cancer cells." (PMID 21119656, 2011). "Here, we take a different approach and estimate the activity of eIF4E, one of the key effectors of mTORC1 function, and investigate whether this reflects response to mTOR inhibition in both tissue culture and in clinical breast cancers." (PMID 21320304, 2011). "Therefore it is important to understand how OPN selectively regulate p70S6K/mTOR phosphorylation leading to NF-κB dependent AP-1 mediated ICAM-1 expression in breast cancer cells." (PMID 20459645, 2010). "Similarly, in a breast cancer model, the phytoalexin resveratrol was found to induce non-canonical autophagy, which was dependent on inhibition of mTOR signaling." (PMID 20368806, 2010). "Further work is needed to determine whether examination of the RMI can identify patients with breast cancer who have baseline activation of mTOR signaling and thus would benefit from treatment with rapamycin or its analogues." (PMID 19778445, 2009). "Since p70S6K overexpression is associated with aggressive disease and poor prognosis of breast cancer patients, the potential downstream targets of p70S6K and the whole PI3K/mTOR/p70S6K pathway identified in our study may have diagnostic value." (PMID 18652687, 2008). "Genes responsive to PI3K, mTOR and p70S6K inhibitions in breast cancer cell lines." (PMID 18652687, 2008). "Breast cancer cells with activated Akt are exquisitely sensitive to mTOR antagonists." (PMID 19430575, 2008). "Epidermal growth factor receptor signalling through the PI3K–Akt pathway results in the activation of the transcription factor nuclear factor-κB (NF-κB) (constitutively active in ERα− breast cancers) and mammalian target of rapamycin (mTOR), an important regulator of protein synthesis." (PMID 18797454, 2008). "However, a recent study demonstrated that ErbB2 increases the synthesis of the vascular endothelial growth factor (VEGF) protein via the activation of mTOR and p70S6K in human breast cancer cells." (PMID 16984645, 2006). "The results of the present study show that specific inhibition of the mTOR pathway by rapamycin may significantly down-regulate Skp2 levels in rapamycin-sensitive breast cancer cells." (PMID 16859513, 2006). "It thus implicates that maintaining mTOR in highly phosphorylated and activated state may attribute breast cancer." (PMID 16288304, 2005). "The role of PI3K/AKT/mTOR pathway may play an important role in the development of Tamoxifen resistance in breast cancer." (PMID 15365568, 2004). "Hormone receptor-positive Breast Cancer (BC) driven by PI3K/Akt/mTOR signaling remains a major therapeutic challenge, particularly in settings where conventional chemotherapy causes severe systemic and reproductive toxicity." (PMID 42038321, 2026).
breast cancer (continued). "In addition, PPARγ activation promotes the expression of its target gene PTEN to inhibit the PI3K/AKT/mTOR signaling, thereby suppressing the proliferation of breast cancer cells and the tumorigenicity and metastasis of cervical, glioblastoma, and liver cancer stem cells." (PMID 41481427, 2026). "Notch activates the PI3K/AKT/mTOR pathway to promote tumor growth.Notch1 activates the mTORC1 pathway.The mTOR pathway cooperates with Notch signaling and metabolic reprogramming to maintain breast cancer stem cell characteristics and promote therapy resistance." (PMID 41050674, 2025). "Indeed, ITM2A has been shown to regulate autophagy in a context-dependent manner: in breast cancer cells, it enhances mTOR-dependent autophagy to inhibit tumor growth, whereas in HEK293 cells, its overexpression disrupts vacuolar ATP synthase and blocks autophagic flux." (PMID 41199749, 2025). "This study investigates, for the first time, the combined use of IVM and MET to determine whether the excessive accumulation of intracellular ROS inhibits the activation of the PI3K/AKT/mTOR signaling pathway, inducing a significant number of autophagosomes in breast cancer cells." (PMID 40699802, 2025). "Furthermore, existing research indicated compound 17 suppressed tumur stemness, proliferation, migration, and epithelial-mesenchymal transition (EMT) in breast cancer by inhibiting the PI3K/Akt/mTOR pathway and stemness-related genes, such as SRY-box2 and Nanog38." (PMID 41006588, 2025). "To further investigate whether hSPAR suppresses breast cancer cell proliferation through mTOR signaling, we transfected control, ΔATG1 + 2, or Flag-hSPAR plasmids into MDA-MB-231 cells in which we blocked mTOR signaling using rapamycin, followed by EdU incorporation assays." (PMID 39875724, 2025). "Therefore, we speculate that TMEM45A is a mechanism of acquired resistance in breast cancer patients by activating the AKT/mTOR signaling pathway and enhancing glycolysis." (PMID 39910045, 2025). "Herein, our study indicates that simultaneous inhibition of PI3K/AKT/mTOR signaling and exogenous FAs uptake using a combination of PI3K and CD36 inhibitors might reduce cell proliferation synergistically in anti-HER2 resistant breast cancer with PTEN-loss." (PMID 39920872, 2025). "Over 30% of metastatic HR+ breast cancer patients develop endocrine resistance, leading to disease progression; the underlying mechanisms are complex and involve ER alterations, cross-talk with growth pathways (PI3K/AKT/mTOR, CDK4/6), and changes in the tumor microenvironment." (PMID 40427153, 2025). "Thus some types of cancer therapy may target intracellular pathways that drive uncontrolled cell growth: examples include inhibitors of the MAPK or P13/AKT/mTOR pathways, such as trametinib for melanoma and everolimus for breast cancer." (PMID 41303504, 2025). "Mechanistically, this transition reflects fundamental aspects of 3D tumor biology, where cells in spheroids can activate survival pathways (e.g., mTOR), which has been reported to have a greater effect on survival in 3D than in 2D breast cancer cell cultures and may contribute to drug resistance." (PMID 41427337, 2025). "As depicted below, breast cancer cells can activate alternative signaling pathways, such as growth factor receptor pathways (e.g., HER2, EGFR, and FGFR), MAPK/ERK pathway, and PI3K/AKT/mTOR pathway, due to alterations (mutations or amplifications) in multiple genes." (PMID 38791941, 2024). "Therefore, we hypothesized that HMMR could be targeted through mTOR, which serves as a critical mediator in advancing the progression of breast cancer." (PMID 38576486, 2024).
breast cancer (continued). "These genes may accumulate somatic mutations in conjunction with mutations and/or amplifications of PIK3CA and AKT3, as well as deletions or mutations of PTEN, TSC1, and INPP4B in the PI3K/mTOR pathway, although not in the majority of breast cancers (BCs)." (PMID 38987766, 2024). "Notably, mTOR inhibitors also reportedly elicit antitumour effects in breast cancer." (PMID 38734930, 2024). "Furthermore, the expression of ZKSCAN3-shRNA profoundly inhibits tumor growth in mice harboring breast cancer xenografts, indicating that suppressing ZKSCAN3 effectively impedes the Akt/mTOR signaling pathway by suppressing the expression of p-Akt and p-mTOR proteins in breast cancer cells." (PMID 39519085, 2024). "Hence, the therapeutic regulation of the PI3K/AKT/mTOR pathway can suppress breast cancer." (PMID 38791386, 2024). "However, the antiproliferative mechanisms of metformin remain undetermined, with several studies having suggested that metformin achieves its antiproliferative mechanism in breast cancer cells via inducing cellular apoptosis by regulating the AMPK/mTOR signaling pathway." (PMID 39796103, 2024). "An example of the improvement with pharmacological therapies is that everolimus (an mTOR pathway inhibitor) in combination with trastuzumab (a HER2 receptor inhibitor) significantly improved survival in patients with trastuzumab-resistant HER2-positive breast cancer." (PMID 39684551, 2024). "To assess whether similar mechanisms of action occurred also in BC upon Bio-nFeR treatment, we performed immunoblot analysis of mammary tumors ex vivo for key factors involved in cellular proliferation and biosynthesis such as pERK, p38, p16, Cyclin D1, mTOR, 4EBP1, and S6RP." (PMID 39497135, 2024). "For instance, studies on lung epithelial cells and breast cancer cells have shown that TiO2 nanoparticles cause G2/M arrest through mechanisms such as DNA damage and oxidative stress, or interference with key signaling pathways that regulate the cell cycle, such as the PI3K/AKT/mTOR pathway." (PMID 39728581, 2024). "Since the enhanced activity of TBK1 (TBK1 K154R) promotes the proliferation of breast cancer cells by targeting the mTOR signaling pathway, it is possible that ubiquitination of TBK1 at different sites may also regulate this proliferation by affecting its activity." (PMID 39061024, 2024). "Notably, some resistant breast cancer patients lack mutations in the PI3K/AKT/mTOR pathway, indicating that nongenetic reprofiling and hyperactivation of the PI3K/AKT/mTOR pathway play significant roles." (PMID 39501277, 2024). "Finally, although our results suggested that RPN1 promoted the proliferation and invasion of breast cancer cells by activating the PI3K/AKT/mTOR signaling pathway, the main target of RPN1 and the specific downstream signaling pathway of PI3K/AKT/mTOR require additional investigation." (PMID 38302629, 2024). "Therefore, we investigated how RPN1 affects the PI3K/AKT/mTOR signaling pathway in breast cancer." (PMID 38302629, 2024). "In BC, subtype differences are reported with activated p-mTOR localizing more often nuclear in triple-negative breast cancer (TNBC) than non-TNBC." (PMID 39696035, 2024). "Hence, overexpression of AURKA could lead to dysregulation in the PI3/Akt/mTOR pathway and an increase in EMT factors associated with more aggressive breast cancer." (PMID 38886738, 2024). "So, acquired resistance to hormone therapy and overexpression of EGFR/HER2 and activation of EGFR/HER2/MAPK pathway may counterbalance the mTOR activation by PI3K/AKT providing breast cancer cells with potent oncogenic signaling and high levels of cytoprotective autophagy." (PMID 37575061, 2023). "Also, previous research has shown that mTOR activities may be higher among patients with breast cancer with earlier (vs. more advanced) stage, lower (vs. higher) grade, smaller (vs. larger) tumors, and ER+ (vs. ER−) tumors." (PMID 36895729, 2023).
breast cancer (continued). "This study demonstrates that the use of an mTOR inhibitor significantly improves clinical outcomes, further highlighting how this route of pharmacotherapy may be beneficial to treating future resistant breast cancers." (PMID 37626871, 2023). "Notably, the STAT3 activity can be positively modulated by mTOR in breast cancer stem-like cells." (PMID 38017510, 2023). "Therefore, inhibiting the PI3K/AKT/mTOR signaling pathway might be a prospective approach for treating breast cancer." (PMID 37641116, 2023). "However, in our breast cancer model, we observed increased p-AMPK levels associated with increased p-mTOR and pro-inflammatory signaling in the TME in RD-fed mice and HFD-fed mice at an early time point of tumorigenesis and at a late time point of tumor progression, respectively." (PMID 36675341, 2023). "In addition, abemaciclib and palbociclib treatment have been shown to downregulate mTOR signaling in small cell lung and breast cancer, providing support that CDK4/6 inhibitors may induce reversible senescence through downregulating mTOR signaling." (PMID 37035239, 2023). "Resistance-associated proteins were Caveolin-1, PgR, mTOR, phosphorylated MEK1/2 (pSer217/221) of the Erk/MAPK signaling pathway, phosphorylated IKKα (pThr23) of the NFκB pathway, the microtubule-associated protein Tau and the basal breast cancer markers CK5, CK6 and Vimentin-pSer56." (PMID 37596623, 2023). "The association between mTOR activity and TNBC has attracted the attention of many researchers because mTOR overactivation is common in many cancers, including breast cancer, especially TNBC, as more activated mTOR is observed in TNBC than in other breast cancer subtypes." (PMID 38156109, 2023). "The mTOR pathway may be crucial in the development of breast cancer." (PMID 36831624, 2023). "Collectively, these findings suggest that class I PI3K and/or mTOR signaling suppresses Wnt/β-catenin signaling in ER− breast cancer cell lines, although whether Wnt activation occurs in primary human ER− breast tumors treated with PI3K inhibitors remains to be determined." (PMID 37471270, 2023). "In addition, mTOR plays a major role in resistance to various therapies in breast cancer." (PMID 37264081, 2023). "GPR30 triggered PI3K/mTOR axis to elevate the extracellular secretion of HMGB1 (High mobility group box 1) in CAFs which led to the activation of the MEK/ERK axis in neighboring ERα-positive breast cancer cells and thereby induction of autophagy to accelerate tamoxifen resistance." (PMID 37900137, 2023). "Indeed, the upregulation of the mTOR pathway in male breast cancer has been shown before using bulk microarray studies, suggesting that MBC patients may benefit from mTOR inhibitors." (PMID 37685859, 2023). "Therefore, mTOR inhibitors have been proposed for treating breast cancer." (PMID 36986711, 2023). "The phosphatidylinositol 3-kinase/protein kinase B/mammalian target of rapamycin (PI3K/AKT/mTOR) signaling pathway involved in cell proliferation, survival, invasion, migration, apoptosis, glucose metabolism, and DNA repair is associated with breast cancer pathogenesis." (PMID 36765810, 2023). "Thus, MYC is a clinically relevant driver of mTORi resistance that may stratify breast cancer patients for mTOR-targeted therapies." (PMID 37642941, 2023). "However, there are also reports that it may also have pro-oncogenic functions in the pathogenesis of breast cancer via the mTOR signaling pathway." (PMID 37759706, 2023). "Moreover, LNT could promote autophagic cell death of breast cancer cells by inhibiting the AKT/mTOR and NF‐κB signaling pathways, thus inhibiting the occurrence and development of breast cancer." (PMID 37249285, 2023). "Furthermore, our work established that andrographolide could inhibit breast cancer cell progression by suppressing the PI3K/AKT/mTOR signaling pathway." (PMID 35684480, 2022).